RNU2-62P (RNA, U2 small nuclear 62, pseudogene)
Gene: Small nuclear RNA gene on chromosome 6 (27,109,790 to 27,109,980, reverse strand). Ensembl gene ENSG00000222800.
Homologues: Orthologues: chimpanzee U2 (99% identical), macaque U2 (50% identical), rabbit U2 (39% identical), macaque U2 (36% identical). Paralogues in human: RNU2-2 (80% identical), U2 (77% identical), RNU2-48P (76% identical), RNU2-6P (76% identical), RNU2-14P (75% identical), RNU2-39P (75% identical), RNU2-26P (75% identical), RNU2-57P (74% identical), RNU2-59P (74% identical), RNU2-64P (74% identical), RNU2-36P (74% identical), RNU2-3P (73% identical), and 65 more.